NUTF2P4 (nuclear transport factor 2 pseudogene 4)
Gene: Processed pseudogene on chromosome 1 (112,748,095 to 112,748,475, forward strand). Ensembl gene ENSG00000234790.
Diseases named in the same sentence as NUTF2P4 in open-access papers:
NUTF2P4 is named in the same sentence as 1 disease in open-access papers, as found by Europe PMC text mining. Sharing a sentence is not in itself a finding about the gene and the disease.
NUTF2P4 shares sentences with these, for which no sentence is quoted: leukemia (1 paper).